IL2 (interleukin 2)
Diseases named in the same sentence as IL2 in open-access papers (continued):
Sharing a sentence is not in itself a finding about the gene and the disease.
tumor (continued). "Indeed, high doses of interleukin (IL)-2 have been shown to suppress RCC progression without inducing tumor ischemia, leading to complete remission in 10–20 % of patients." (PMID 26772545, 2016). "However, following stimulation with α-c-myc tag monoclonal antibody or the tumor cells 24JKERB, we detected a range of cytokines, including IL-4, IL-2, IL-17A, TNF-α, IL-6 and IFN-γ from CAR T cells, while no significant response was observed from WT T cells." (PMID 27153556, 2016). "Tumor fragments were cultured in IL-2 in the presence or absence of anti-4-1BB antibody." (PMID 27777771, 2016). "We next examined the cytokine profiles of tumor-infiltrating lymphocytes following ex vivo stimulation, and found that T cells in the CCR4 antagonist-treated group secreted significantly higher amounts of IFN-γ, IL-2, and TNF-α than T cells in the control groups (P < 0.05 for each)." (PMID 27177223, 2016). "Moreover, studies have shown that, in the highly dynamic tumor-immune system, the expression of PD-L1 in tumor microenvironment can also be induced by CD8-positive T cells, as well as cytokines such as interferon γ, IL-2, IL-7, IL-15, and IL-21 in a positive feedback mechanism." (PMID 27120796, 2016). "In the current study, we further defined the mechanisms involved in B cell-mediated killing of tumor cells and found that activated B effector cells killed tumor involving the CXCR4/CXCL12 and perforin pathways as well as the Fas/FasL interaction, and can be augmented by IL-2." (PMID 27528023, 2016). "However, such external anti-CD3/CD28 or IL-2 models are artificial and do not reflect the actual state in tumor microenvironment." (PMID 26895379, 2016). "Also, mice that were injected only with PBMCs+IL-2 but without any tumor, showed no engraftment of NK cells." (PMID 26802025, 2016). "Because LPS bolstered the persistence of infused CD8+ T cells and mediated curative responses in irradiated mice, we hypothesized that LPS administration might drive tumor regression without the need for vaccination or IL-2." (PMID 26885368, 2016). "Our in vitro experiments demonstrated that IL-2 modulated expression of CD25 on B cells after activation /expansion (A/E) before adoptive transfer; enhanced CXCR4 expression on B cells; augmented CXCL12 production by 4T1 tumor cells, and increased production of perforin by B cells." (PMID 27528023, 2016). "Differences in the sensitivity or response of specific lymphocyte subsets between different individuals may account for why only a fraction of patients with non-cutaneous visceral metastases respond to HD IL-2 therapy with an objective tumor shrinkage." (PMID 27153543, 2016). "Multiple studies over many years have tried to identify biologic and immunologic parameters to pre-select patients for sensitivity to HD IL-2, but to date there is no biomarker for response related to the tumor itself or to the patient’s immune profile that has been prospectively validated." (PMID 27891227, 2016). "In addition, OSCSCs differentiated with supernatants from IL-2 + anti-CD16mAb + sAJ2 NK cells demonstrated inhibition of tumor growth when compared to either untreated OSCSCs or those treated with IL-2 + anti-CD16mAb in the absence of sAJ2." (PMID 26697005, 2015). "Finally, IFN-α2 and IL-2 also induced tumor accumulation of NK cells, which are capable of killing tumor cells expressing low levels of MHC class I and thus compensate for the poor tumor recognition of T-cells." (PMID 26107883, 2015). "However, natural killer (NK), but not T cells were found to kill mHsp70-positive tumor cells after activation with a naturally occurring Hsp70 peptide (TKD) plus low dose IL-2 (TKD/IL-2)." (PMID 25926832, 2015). "Tumor-reactive T cells from lymph nodes can be further expanded ex vivo in the presence of an anti-CD3 stimulus with or without CD28 engagement in addition to interleukin-2 to treat established tumors." (PMID 25990075, 2015).
tumor (continued). "Although other mechanisms may contribute to the therapeutic responses, our data suggests that CTLA-4 blockade may help recruit NK cells to the tumor microenvironment while IL-2 (alone and in combination with CTLA-4 blockade) altered the maturation of tumor-infiltrating NK cells." (PMID 25992289, 2015). "In addition, complete tumor regression was achieved with the combination of ESAT-6 and IL-2 genes." (PMID 26213962, 2015). "Furthermore, whereas administration of this anti-IL-2/IL-2 complex altered the ratio of Tconvs to Tregs in favour of Tregs in secondary lymphoid tissues, the ratio of Tconvs to Tregs in the tumor did not change." (PMID 26433463, 2015). "While use of these agents, alone, or in combination with non-specific immuno-adjuvant therapies like HD IL-2, has not revealed a survival advantage, active specific therapy, that is employment of autologous dendritic cells (DCs) as vectors for tumor-specific antigens, has." (PMID 29546098, 2015). "Based on the results of the tumor challenge and growth, it was concluded that PAP-specific immune activation occurred in the mice treated with the PAP-fused cytokines, and the antitumor effects were significantly enhanced by the additional cytokine (IL2, IL4 and IL7) fusion proteins." (PMID 25632844, 2015). "Treatment of MP2 with fixed NK cells treated with IL-2 + anti-CD16mAb + sAJ2 + anti-TNF-α had slight enhancing effect on tumor growth, whereas fixed NK cells obtained from anti-IFN-γ in combination with IL-2 + anti-CD16mAb + sAJ2-treated NK cells enhanced tumor cell growth substantially." (PMID 26697005, 2015). "We have shown in previous studies that transgenic expression of IL-2 on EFT cells enhances the immunostimulatory activity but could not completely inhibit the growth of the tumor cells." (PMID 26579494, 2015). "Interestingly, the antisera did not affect the anti-tumor efficacy of IL-2 therapy in BDF mice bearing the colon 38 adenocarcinoma." (PMID 24884532, 2014). "IFN-gamma and IL-2 secretion from splenocytes and tumor-infiltrating CD8+ T cells from mice injected with Rv0652-OVA-DCs and then re-stimulated with OVA257–264, was higher than the IFN-gamma and IL-2 secretion from splenocytes and tumor-infiltrating CD8+ T cells from mice injected with OVA-DCs." (PMID 25102137, 2014). "However, the mechanisms of CIK cell proliferation and acquisition of cytolytic function against tumor induced by IL-2 and IL-15 have not been well elucidated yet." (PMID 25108500, 2014). "In an effort to optimize IL-2 therapy, the renal cell “SELECT” trial was designed to assess if the patient population could be selectively enriched based on carbonic anhydrase IX overexpression within the tumor besides other factors." (PMID 28326252, 2014). "It is therefore promising that our PSCA-CAR-engineered T cells are able to delay tumor growth in vivo without irradiation preconditioning or IL-2 support, though it may be beneficial to combine those treatments in the future for better effects." (PMID 24438073, 2014). "However, we speculated that pre-activation of T cells by interleukin 2 (IL-2) in combination with anti-CD3/anti-CD28-coated beads and subsequent co-receptor-mediated cross-linkage to tumor cells could perhaps already be operative." (PMID 24751697, 2014). "Thus, activation of T cells to produce Th 1 cytokines (IL-2 and IFN-γ) that further activated cytotoxicity of splenocytes may have contributed to the lower mitotic division in the tumor." (PMID 23710232, 2013). "We show that by acting via endogenous CD40L and IL-2, and acquired peptide-MHC-I (pMHC-I) complex signaling, CD4+ Th cells enhance survival of transferred effector CTLs and their differentiation into the functional memory CTLs capable of protecting against highly-metastasizing tumor challenge." (PMID 23785406, 2013).
tumor (continued). "No anti-tumor effector cells or cytokines that potentiate anti-tumor immunity (i.e., IFNγ and IL-2) could be detected in spleens of mice injected with fibrosarcoma cells transfected with IL-1β or ssIL-1β or with the violent parental cells." (PMID 23847618, 2013). "One reported mechanism of tumor cell escape is hypoxia-induced shedding- and decreased surface expression of MHC class I chain-related (MIC) molecules resulting in reduced cytotoxicity of IL-2 stimulated peripheral blood lymphocytes (PBL) against prostate cancer cells." (PMID 23724099, 2013). "However, PPD significantly increased the NK cell activity and levels of IL-2 and IFN-γ, suggesting that PPD may improve cellular immune function in CTX-treated tumor-bearing mice." (PMID 23407364, 2013). "Our data suggest that cellular immunotherapy using aATC with low levels of IL-2 and IFN-γ will not only target the tumor cells but may reverse the suppressive tumor environment to allow recruitment of CTLs and NK cells at the tumor sites and may induce an endogenous anti-tumor immune responses." (PMID 23394575, 2013). "Importantly, we demonstrate that in vivo depletion of regulatory T cells (Tregs) and CD8+ T cells in FBL-3-bearing DEREG transgenic mice augments IL-2 and GzmB production by CD4+ T cells and increases FV-specific CD4+ T-cell effector and cytotoxic responses leading to the complete tumor regression." (PMID 22890822, 2013). "Alpha-interferon, interleukin-2, sorafenib, sunitinib and everolimus were administered to our patient, but tumor progression could not be suppressed." (PMID 22738297, 2012). "In our studies, while modest direct anti-tumor effects were obtained using this approach, combination of MRF/magnetic field treatment with immunotherapy using suboptimal doses of agonistic anti-CD40/IL2 resulted in significantly greater and, importantly, systemic anti-tumor responses." (PMID 23133545, 2012). "In order to assess whether signaling responses also were altered in tumor-infiltrating T cells in SLL/CLL and MZL, tumor samples were stimulated with IL-2, IL-7 and IL-15 for 15 minutes and phospho-protein levels were evaluated in the CD5+ CD20- T cell fraction." (PMID 23072591, 2012). "Given the observation of PSK and docetaxel-induced TIL enhancement, we further analyzed whether any changes in IFN-γ, IL-2, TNF-α, TGF-β, perforin, granzyme B and FoxP3 mRNA expression in the tumor micro-environment could be observed in response to the treatments." (PMID 22159900, 2012). "Without lymphodepletion or IL-2 administration, transferred T cells could persist for >16 months, established anti-tumor immunological memory in vivo, trafficked to tumor, and induced clinical responses." (PMID 22279573, 2012). "Thus, our data suggest the expansion of Treg cells by the local delivery of IL-2 does not significantly impede the therapeutic anti-tumor effect generated by the therapeutic HPV DNA vaccine." (PMID 22509395, 2012). "However, when fused to GM-CSF, IL-2, or IL-4, these recombinant molecules elicited anti-tumor immunity when administered without carrier or adjuvant." (PMID 23162790, 2012). "However, with the current study, we have shown that the specific delivery of IL-2 with the NKG2D-Fc system led to both the expansion of tumor antigen-specific CD8+ T cells at the tumor loci and an improved therapeutic anti-tumor effect generated by the therapeutic DNA vaccine." (PMID 22509395, 2012). "Notably, this reflected a unique property of anti-OX40/IL-2 immunotherapy as treatment with anti-OX40/IL-4c or anti-OX40/IL-15c did not affect tumor growth or survival (data not shown)." (PMID 22496812, 2012). "Similar results were also seen in co-cultures of tumor and NK cells in the absence of IL2 (right)." (PMID 21559505, 2011). "We have shown for the first time that a recovery of the Ca response of TIL may be observed a few hours after disrupting the tumor microenvironment, without the need to be supplemented with exogeneous IL-2." (PMID 21408177, 2011).
tumor (continued). "However, whether the IL-2/IL-2 receptor functions in ALCL cells and how this signaling affects the tumor remain unclear." (PMID 23675235, 2011). "In addition to the established, albeit toxic and rather ineffective treatments of interferon alpha in the adjuvant setting and Interleukin 2 in the advanced setting, new therapies with anti-CTLA-4 antibodies or specific (individualized) tumor vaccines are being developed." (PMID 20224761, 2010). "In contrast, unlike IL-2, IL-15 does not promote the expansion of Tregs and when overexpressed in human T cells prolonged the expression of antiapoptotic genes thus the persistence of tumor specific cells and enhanced their antitumor responses." (PMID 21076522, 2010). "Moreover, maintenance of in vivo cytotoxicity against tumor cells was not necessarily dependent on the sustained administration of large doses of exogenous interleukin (IL)-2." (PMID 20799994, 2010). "Our group has identified a membrane form Hsp70 on tumor cells as a tumor-specific recognition structure for a perforin-independent, granzyme B-mediated attack by allogeneic and autologous NK cells that have been pre-stimulated with Hsp70 peptide TKD plus low dose IL-2." (PMID 21179573, 2010). "Moreover, IL-2 may affect different cell types, including CD4+ T cells, NK cells, macrophages and B cells, resulting in anti-tumour immunity." (PMID 19935800, 2009). "Tumour-infiltrating lymphocytes (CD4, CD8, Foxp3), mast cells (MCs) (tryptase and chymase), microvessel count (MVC) and VEGF were determined by immunohistochemistry in two series of MPM patients: 60 patients treated with intra-pleural preoperative IL-2 and 33 patients untreated." (PMID 19935800, 2009). "Seven mice (70%) of the Neuro-IL2/IL12 vaccine group and nine (90%) of the AJ-IL2/IL12 vaccine group remained tumour free for over 3 months, a significant improvement over the control group where 100% of the mice developed tumours and were killed at 12 days post engraftment (P<0.01)." (PMID 17595664, 2007). "However, approximately 50% of all IL-21+ IL-2 treated mice in three experiments did not exhibit tumor growth, and by day 42–49 manifested complete regression of the tumor." (PMID 16772043, 2006). "IL-2 has no direct impact on tumour cells but requires NK and T-cells for tumourlysis." (PMID 16434984, 2006). "Thus, a large confirmatory randomised phase III trial of IL-2 with and without histamine in mRCC appropriately stratified for monocytes and neutrophils in blood and tumour tissue is warranted." (PMID 16434984, 2006). "Similarly, unvaccinated tumor-bearing control mice which were irradiated and treated with IL-21 or IL-21 + IL-2 only had comparable rapid tumor growth (data not shown)." (PMID 16772043, 2006). "Cultures of tumor infiltrating lymphocytes secreted significantly higher amounts of IgM and IgG than the PBL of either patients or controls in good agreement with the increased levels of IL-2 and IL-10, since these cytokines are involved in B cell activation and enhance immunoglobulin synthesis." (PMID 15450122, 2004). "However, enhanced nonspecific, cytokine-driven killing activity was observed against each cell line since a total repression of tumour cell growth occurred at lower effector doses than that observed in the absence of IL-2." (PMID 12671714, 2003). "Although in vitro detection of cytolytic activity does not always correlate with in vivo tumour rejection, the potential of the C595scFv-Fc-IL2 fusion protein to activate immunocompetent resting NK and preactivated T cells after binding to MUC1-positive tumour cells is clearly demonstrated." (PMID 12966437, 2003). "Neither gender, time from primary tumour to occurrence of metastases (<12 months vs ⩾12 months), type of first-line immunotherapy (IL-2-based treatment vs IFNα alone), number of sites before second-line treatment (1 vs >1) nor general status (Karnofsky ⩾90 vs <90%) reached statistical significance." (PMID 14676797, 2003).
tumor (continued). "At later stages of tumour growth (day 23), tumours themselves induced significant fluid retention in the lungs and the kidney, which was not aggravated further with the second round of IL-2 therapy." (PMID 8546905, 1996). "We tested whether NG-nitro-L-arginine methyl ester (L-NAME), an inhibitor of nitric oxide (NO) synthesis, can prevent interleukin 2 (IL-2)-induced capillary leakage in tumour-bearing mice without compromising the therapeutic benefits of IL-2." (PMID 8546905, 1996). "Histological examination of tumours expressing either IL-2 or IL-4 alone shows a non-specific inflammatory reaction with an increased tissue infiltrate of immune effectors (monocytes/macrophages, lymphocytes, granulocytes) localised around the tumour." (PMID 8679459, 1996). "The benefit of combined IL-2 + IL-4 expression results from a local rather than systemic effect as the growth of tumours from cells expressing IL-2 or IL-4 alone injected at distant sites was comparable with a single inoculation of cells expressing either cytokine alone." (PMID 8679459, 1996). "However, when cells expressing single cytokines IL-2 or IL-4 were mixed and injected at the same site, in comparison with the clonal population of cells expressing combined IL-2 + IL-4, tumour growth was characteristic of IL-4 alone rather than IL-2 + IL-4." (PMID 8679459, 1996). "However, although successful in treatment studies, neither wild-type nor combined IL-2 + IL-4 expressing cells were able to vaccinate animals against a subsequent challenge with live wild-type tumour." (PMID 8679459, 1996). "Several cytokines--interleukin 2 (IL-2), tumour necrosis factor alpha (TNF-alpha) and interferon gamma (IFN-gamma)--and prostaglandin E2 (PGE2) known to modulate tumour growth and metastasis were examined to determine whether they regulate nm23 expression in JAR in vitro." (PMID 8080727, 1994). "However the mechanisms of action of secreted IL-2 and IL-4 have not been compared in a single rodent tumour." (PMID 8347485, 1993). "Notably, after treatment, proinflammatory cytokine secretion was significantly increased by tumor‐border, but not by non‐tumor lung tissue slices, compared with the medium control, evidenced by higher levels of IFNγ (1.7‐fold), IL‐2 (1.4‐fold), and Perforin (1.5‐fold)." (PMID 40952312, 2025). "Therefore, low levels of IL-2 at baseline may result in the preferential expansion of long-lived memory CD4 + T cells but not CD8 + cytotoxic T-cell populations, thus potentially having an impact on anti-tumor activity and OS." (PMID 39984775, 2025). "In addition to tumor cell killing, we measured the secretion of the pro-inflammatory cytokines IFN-γ, TNF-α and IL-2, which might be relevant on the one hand for potential side effects but also on the other hand for the anti-tumor response and the modulation of the TME." (PMID 38582787, 2024). "XTX202, an IL-2 mutein linked to an inactivation domain that could be cleaved by tumor proteases in the TME, induced potent tumor growth inhibition without systemic toxicity or peripheral immune activation in mouse models, and it is currently undergoing clinical evaluation." (PMID 38773064, 2024). "IL‐2‐Fc and ICK caused significant decreases in circulating CD4+ T cells in both models, although no significant changes in circulating Tregs were observed in both models, suggesting changes in circulating T cell frequencies do not correlate with changes seen within the tumor." (PMID 38317590, 2024). "Furthermore, NKTR-214 provided a 500-fold greater tumor exposure than non-PEGylated IL-2." (PMID 39169031, 2024). "Thus, IL-2 and CD25 may be targets for controlling Tregs survival and suppressive function, and the combination of radiotherapy with this approach may enhance anti-tumour effect." (PMID 38259489, 2023).